ALB (albumin)
Diseases named in the same sentence as ALB in open-access papers (continued):
Sharing a sentence is not in itself a finding about the gene and the disease.
cardiovascular disease (continued). "Ingenuity pathway analysis showed that the top networks with high confidence levels include albumin and ERK signaling pathways involved in cardiovascular disease, organismal injury and abnormalities, and organ morphology." (PMID 30430305, 2018). "Participants who were included in the study were less likely to be white or have cardiovascular disease (CVD), had slightly lower urea, hemoglobin, and higher albumin as compared with those excluded." (PMID 28178126, 2017). "Although, the regulation of Aβ peptides by albumin in cardiovascular disease has not yet been investigated." (PMID 38398429, 2024). "The exclusion of patients with prior cardiovascular disease or those who died in the first year of follow-up did not materially affect the results from the albumin to total cholesterol ratio analyses." (PMID 35755025, 2022). "Of those parameters, 15 metrics with the highest prediction values were identified: gender, age, BUN, Cr, INR, albumin, MCV, RDW, MCH, WBC, segmented neutrophil count, lymphocyte count, and past medical history of neurological, respiratory, and cardiovascular disorders." (PMID 35098205, 2021). "As cardiovascular diseases (CVDs) are the common complications in CKD patients, oxidative stress aggravated by oxidized ALB-induced neutrophil respiratory burst might be responsible for the complication." (PMID 33804859, 2021). "Recently, the neutrophil-to-lymphocyte ratio (NLR), platelet-lymphocyte ratio (PLR), and C-reactive protein-to-albumin ratio (CAR) have been suggested as useful and cost-effective prognostic biomarkers in various diseases, including malignant and cardiovascular diseases." (PMID 29293605, 2018). "Recent studies have suggested that neutrophil-to-lymphocyte ratio (NLR) and C-reactive protein-to-albumin ratio (CAR) are emerging markers of disease activity and prognosis in patients with chronic inflammatory diseases, cardiovascular diseases, or malignancies." (PMID 29293605, 2018). "ER group had large proportions of cardiovascular disease and a central venous catheter (CVC) at initiation of dialysis, and had higher baseline Cr and albumin relative to LR group, whereas white blood cell (WBC) count, corrected Ca level, and phosphorous level were lower." (PMID 26030256, 2015). "We examined the association between the urine albumin/creatinine ratio (UACR) and hs-cTnT levels in 1354 participants without overt cardiovascular disease in a community-based, cross-sectional study in Beijing, China." (PMID 26301504, 2015). "Cardiovascular diseases are also accompanied by the reduction of negative acute phase reactants such as albumin, transferrin, transthyretin, retinol-binding protein, antithrombin, and transcortin." (PMID 24049653, 2012). "Cardiovascular disease is also accompanied by the reduction of negative acute phase reactants such as albumin, transferrin, transthyretin, retinol-binding protein, antithrombin, and transcortin." (PMID 24049653, 2012). "The high-sensitivity C-reactive protein to albumin ratio (CAR) or C-reactive protein to albumin has emerged as a valuable prognostic indicator in various medical conditions including solid tumors, hematological malignancies, cardiovascular diseases and respiratory diseases." (PMID 40435309, 2025). "While previous studies were conducted in generally healthy, community-living populations with 24 h urine albumin excretion < 30 mg/day or without cardiovascular disease at baseline, our study was performed in CKD patients who mostly had proteinuria and several medical comorbidities at enrollment." (PMID 36151235, 2022). "A decrease in serum albumin levels in diabetic individuals may not be useful as an early marker for cardiovascular disease development." (PMID 31737067, 2019).
cardiovascular disease (continued). "Cardiovascular disease was far more common in other ESRD patients than among LN- or GN-ESRD patients, and those with LN-ESRD were less likely to report smoking and also had lower body mass index (BMI) and lower levels of albumin and hemoglobin than those with GN-ESRD or other ESRD." (PMID 25884409, 2015). "Here we wanted to investigate the combined effects of SHS extracts and glycated albumin to determine whether or not a diabetic who is exposed to tobacco smoke would have an increased likelihood for the development of cardiovascular diseases." (PMID 20604957, 2010). "Age, the prevalence of cardiovascular disease, Charlson comorbidity index, SARC-F, Kt/V, and C-reactive protein were higher among non-survival patients, while BMI, serum albumin, creatinine, phosphorus, and nPNA were higher among survival patients." (PMID 33142777, 2020).
retinopathy (99 papers, 2007 to 2026). "The association between serum albumin levels and retinopathy was assessed using logistic regression after adjusting for potential confounders." (PMID 38369636, 2024). "After adjusting for potential confounders, we observed a significant inverse association between serum albumin levels and the incidence of retinopathy." (PMID 38369636, 2024). "In fact, previous studies have shown that patients with retinopathies exhibit increased levels of vitreous albumin, possibly as a result of the vascular leakage associated with the disease." (PMID 32858986, 2020). "In CM, AKI was associated with the presence and severity of retinopathy (p < 0.05) and increased cerebrospinal fluid albumin suggestive of blood-brain barrier disruption." (PMID 31109328, 2019). "Levels were associated with 13–16 year progression risk of retinopathy (>3 sustained microaneurysms, P = 0.0004) and albumin excretion rate (P = 0.0038), the latter despite adjustment for HbA1c." (PMID 26864236, 2016). "First, prospective cohort studies are needed to establish the causal and dynamic relationship between the albumin-lymphocyte-CRP factor and the progression of retinopathy." (PMID 40151349, 2025). "The top 10 features contributing to the RF model were, in descending order, urine albumin, BMI, numbness in extremities, potassium, serum albumin, creatinine, retinopathy, HbA1c, segmented neutrophils, and fasting blood glucose." (PMID 41473241, 2025). "The model drugs were bovine serum albumin and bevacizumab (an agent that slows neovascularization due to retinal disorders)." (PMID 41012510, 2025). "The cut-off value of albumin assessed by ROC curve is 4.02 mg/dl with 47.62% sensitivity and 90.80% specificity (area under curve 0.747) for predicting retinopathy." (PMID 31777503, 2019). "ROC analysis in diabetic patients showed albumin had a predictive value for retinopathy and CAD complications in this cohort." (PMID 31777503, 2019). "Regardless numerous studies carriedout worldwide, daily urine albumin secretion remains to be standard marker ofnephropathy development, while ophthalmologic examination stands for diagnosisof retinopathy." (PMID 17641733, 2007). "Neither severe retinopathy (i.e. requiring either retinal photocoagulation or specialist ophthalmology review) nor elevated urinary albumin/creatinine ratio was associated with C-peptide status." (PMID 32034440, 2020). "We have previously defined T2DM with nephropathy by albumin excretion-creatinine ratio (AER) and analyzed prevalence and the risk factors for the complication, and defined T2DM with retinopathy by photography and assessed the correlation of the retinopathy to cardiovascular autonomic scoring scale." (PMID 27446820, 2015). "Descriptive analysis showed that urine albumin–creatinine ratio did not demonstrate a linear association with probability of sight-threatening retinopathy; a natural log transformation was more suitable for the model." (PMID 24823871, 2014). "At final adolescent visit, 20% had CAN abnormality, 30% abnormal pupillary response, 20% albuminuria, 40% early elevation of albumin excretion rate (AER) and 45% retinopathy." (PMID 40302950, 2024). "Although total calcium levels and albumin-adjusted calcium levels have been reported to be reasonably correlated to ionized calcium levels, further studies are needed to explore the association between retinopathy and ionized calcium levels in non-diabetic individuals." (PMID 36531449, 2022). "The major endpoint of the study is the change in albumin excretion; secondary endpoints include markers of CVD, renal function, retinopathy, quality of life combined with assessment of compliance and potential health economic benefits." (PMID 20017932, 2009).
retinopathy (continued). "Multivariate logistic regression was used to analyze the relationship between blood urea nitrogen (BUN), creatinine (Cr), uric acid (UA), urine albumin(ALB), albumin-to-creatinine ratio (ACR), estimated glomerular filtration rate (eGFR), and diabetic peripheral neuropathy and retinopathy." (PMID 38174078, 2023). "In the no retinopathy group, 83.03% had normal albumin levels in urine, whereas 16.96% had microalbuminuria." (PMID 35155044, 2022). "In addition, VEGF immunoreactivity is correlated with increased vascular permeability, as indicated by human serum albumin (HSA) immunostaining, and appears to be increased in diabetic subjects before the onset of retinopathy." (PMID 33504108, 2021). "Additional adjustment for history of CVD, retinopathy, eGFR, and urinary albumin excretion did not materially alter the results, although statistical significance was not retained in the associations of IGP with CWSmean (model 6)." (PMID 31727061, 2019). "In DCCT, C-peptide responders (C-peptide response above 0.2 nmol/l) had significantly lower rates of albumin excretion (P = 0.027) and nearly significantly lower prevalence of retinopathy (P = 0.057) than non-responders, after adjusting for age and sex." (PMID 31803138, 2019). "Mean ± SD of urine albumin level in patients with proliferative retinopathy, non-proliferative retinopathy and without retinopathy was 19.8 ± 6.6, 18.5 ± 6.7 and 16.8 ± 6.3 mg/day respectively that the difference was significant (P= 0.012)." (PMID 25848640, 2015). "Mean (±SD) of albumin in patients with proliferative retinopathy was significantly more than it in patients without retinopathy (P= 0.009)." (PMID 25848640, 2015). "Further adjusting model 2 for retinopathy and albumin-to-creatinine ratio did not change the results of the analysis." (PMID 25299316, 2014). "The NPDR children demonstrated a significantly longer duration of the disease in addition to higherHbA1c, albumin excretion rate, C-reactive protein, as well as systolic blood pressure than those without retinopathy." (PMID 17641733, 2007). "Sixth, after additional adjustment for a history of CVD, eGFR, urinary albumin excretion, and the presence of retinopathy (data not shown, for retinal and skin analyses, data on these additional covariates were available in 1884 and 1254 individuals respectively)." (PMID 29077770, 2017). "In this study, we did not consider those T2DM with normal fundus but with abnormal estimated glomerular filtration (eGFR) or Albumin-to-creatinine ratio (uACR), that is DKD patients without retinopathy." (PMID 36733289, 2022). "In relation to those without retinopathy, the NPDR children demonstratedsignificantly longer duration of the disease, they had higher HbA1c, urine albumin excretion rate,CRP level, as well as the systolic blood pressure." (PMID 17641733, 2007). "The NPDR children demonstrated a significantly longer duration of the disease in addition to higher HbA1c, albumin excretion rate, C-reactive protein, systolic blood pressure, as well as TNF-α and IL-6 levels than those without retinopathy." (PMID 17641733, 2007). "However, the patients with T1DM and without retinopathy had significantly higher serum levels of HbA1c and CRP, higher urinary albumin excretion, and higher systolic blood pressure values in comparison with the control group (P < 0.05)." (PMID 23671881, 2013).
heart disease (98 papers, 2012 to 2026). "Among patient-related factors, ASA class of III or greater, pre-existing cardiac disease, pre-existing neurologic disease, higher number of pre-existing comorbidities, and low albumin were associated with increased unadjusted odds of L-PRF." (PMID 35568812, 2022). "Some authors have shown that excretion of peritoneal albumin was significantly associated with cardiac diseases, resulting in dialysis withdrawal." (PMID 29699499, 2018). "Further multivariate analysis showed that increased ΔHS was associated with being female (β = –2.87, P = 0.003), heart disease (β = 2.69, P = 0.04), high baPWV (β = 0.27, P = 0.04), low hemoglobin (β = –1.10, P<0.001), and low serum albumin (β = –5.21, P<0.001)." (PMID 25386836, 2014). "Thus, low albumin, cholesterol, and lymphocyte levels may signal increased risk in heart disease patients." (PMID 40984946, 2025). "Specifically, we assessed the utility of the CALLY index, a score based on straightforward biochemical markers—CRP, serum albumin, and lymphocytes—which has previously demonstrated prognostic value in non-cardiac diseases." (PMID 39767174, 2024). "Previous studies have demonstrated that the CALLY index, calculated using C-reactive protein (CRP), albumin, and lymphocytes, is a reliable indicator of mortality in patients with non-cardiac diseases." (PMID 39767174, 2024). "A lower baseline HMS was also present in patients who were less healthy in general, as indicated by a greater prevalence of cardiac disease and lower average albumin." (PMID 39449723, 2024). "In line with a previous report, our results indicate that the GNRI is a more dependable index than serum albumin or BMI alone for predicting heart disease in Korean adults." (PMID 37964931, 2023). "Type of dialysis (PD or HHD), comorbid conditions such as diabetes and cardiac diseases, blood and serum markers such as albumin, phosphate, and hemoglobin levels have been shown to be associated with dialysis withdrawal." (PMID 29699499, 2018). "Individuals in the MIF-1hi group had longer-lasting heart disease (8 vs. 12 years, p = 0.028), lower levels of serum albumin (42.7, IQR 38.1–46.2 g/L vs. 45.2, IQR 42.8–46.8 g/L, p = 0.035), and worse kidney function (eGFR 64.9 ± 3.3 vs. 77.0 ± 3.7 mL/min/m2, p = 0.019)." (PMID 40426915, 2025). "This association remained significant and became stronger after adjusting for confounders, including sex, serum albumin, BMI, smoking status, alcohol consumption, subjective health, education level, regular exercise, lifestyle disease, and heart disease (adjusted HR [aHR], 1.88; 95% CI, 1.08-3.26)." (PMID 40992028, 2025). "In multivariate analysis, a previous cardiac disease (HR 2.39 95% CI 1.25-4.59, p = 0.009), and baseline serum ammonia (HR 1.01, 95% CI 1.00-1.02, p = 0.022) and baseline albumin (HR 0.93, 95% CI 0.88-0.99, p = 0.018) levels were associated with OHE in the elective group." (PMID 41159057, 2025). "The patients who received a renal transplant had less cardiac disease and a higher average albumin." (PMID 39449723, 2024). "Albumin is a carrier protein and marker of protein synthetic function, thus it is conceivable that its insufficiency could manifest in cardiac disease." (PMID 29117214, 2017). "The albumin-bilirubin (ALBI) score has demonstrated prognostic value in a range for liver and heart diseases." (PMID 39713194, 2024). "Urea-BUN, albumin, HCT, Hg, MCHC, RDW values ​​should be carefully monitored for the first 48 hours in patients with PCAS with cardiac disease." (PMID 32025402, 2019). "Age, height, weight, presence of cardiac disease, PSA, preoperative hematocrit, and albumin level demonstrated statistically significant differences between RRP and RALP groups." (PMID 26844486, 2016). "Accordingly, the researchers propose that in patients with non-cyanotic cardiac disease undergoing simple surgery, albumin 5% is a suitable substitute for fresh frozen plasma." (PMID 37342666, 2023).
heart disease (continued). "The first was men under the age of 60 years with chronic kidney disease (defined as eGFR <60 mL/min or albumin–creatinine ratio (ACR) >2.5 mg/mmol) and cardiac disease (including ischaemic heart disease, cardiomyopathy, dysrhythmias or cardiac failure) and hearing loss." (PMID 35977816, 2023). "However, we observed obvious heterogeneities in BUN (=81%), osmolality (=78%), C-peptide (=77%), urine albumin (=77%), uric acid (=66%), MMA (=58%), retinol (=57%), and heart disease (=53%)." (PMID 36438912, 2022). "Moreover, they had lower levels of lymphocyte count, albumin, EGFR, and TBIL, and higher levels of SBP, cardiac biomarkers (Hs-TnI, CK-MB, Myo, and NT-proBNP), WBC, neutrophil, inflammatory factors (Hs-CRP, IL-2R, IL-6, IL-8, and TNFα) and D-dimer in comparison to survivors without cardiac disease." (PMID 33553255, 2020).